CCND1 (cyclin D1)
Diseases named in the same sentence as CCND1 in open-access papers (continued):
Sharing a sentence is not in itself a finding about the gene and the disease.
tumor (continued). "This, in combination with the absence of FGFR3 and CCND1 protein expression, suggests that these tumours have a GU tumour‐cell phenotype." (PMID 28195647, 2017). "Thus, cyclin D1 physically and functionally interacts with pSmad2/3 and Smad4 in both HCC cells and HCC primary tumor tissues, which further implicates in the pathogenesis of the disease, such as a poor prognosis for HCC patients." (PMID 28415588, 2017). "Western blot analysis of tumor protein extracts revealed that Blimp1 was effectively knocked down in vivo, and its down-regulation correlated with decreased FAK activation and expression and decreased expression of Cyclin D1." (PMID 28442738, 2017). "Moreover, 17 cell cycle markers, including CDK2, CCND1 and CDKN1A, 20 cellular growth and proliferation markers, and other biomarkers for NB or other tumours, were also identified." (PMID 28246384, 2017). "Among them, CCND1 has been reported as oncogene before, whereas the functions of the other five candidate target genes in tumor have not been defined yet." (PMID 28602785, 2017). "Expression levels of MYC and CCND1 were significantly elevated in tumor tissues than those in normal tissues (2.80-fold with MYC probe #202431, p=4.0x10-14; 1.91-fold with CCND1 probe #208711, p=8.96x10-7; and 2.11-fold with CCND1 probe #208712, p=8.79x10-9)." (PMID 29245969, 2017). "In addition, results from in vivo nude mouse xenograft tumor model showed that XIST knockdown reduced the tumor size, the protein levels of CDK1 and Cyclin D1 in tumors, and increased P21 protein level in tumors." (PMID 29371940, 2017). "Moreover, SLC7A11-AS1 knock down was able to increase proliferation and promote cell cycle progression in tumor cells, as well as up-regulate Gclm, ASK1, c-Jun, and cyclin D1 expression and down-regulate p38 expression." (PMID 29348845, 2017). "With the results above, KCTD11 was found to be regulating not a few molecules related to tumor progression, such as Cyclin D1, CTGF, MMP9 and Slug." (PMID 28465479, 2017). "Also IBC tumor samples showed amplifications in the following: MYC (8/32; 25%), CCND1 (7/32; 22%), ErbB2 (5/32; 16%), MCL1 (6/32; 19%), and FGFR1 (3/32; 9%)." (PMID 28271309, 2017). "In the current studies increased iNOS staining of macrophages was observed in the cyclin D1 stroma tumors in vivo (data not shown), consistent with a protumorigenic role of the cyclin D1 stromal-augmented tumor inflammation." (PMID 29137220, 2017). "Additionally, tumor tissues from patients with the GG genotype show increased AKT1 and Cyclin D1 expression compared with tumor tissues from patients with the AA and AG genotypes." (PMID 28045918, 2017). "Altered expression of several biomarkers including increased expression of activated AKT, p21 and cyclin D1 and reduced expression of pro-apoptotic marker BAX was observed in the tumor adjacent normal (TAN) skin of acute ultraviolet B treated trigenic RXRαep−/− mice." (PMID 29121869, 2017). "Thus, the nuclear retention of cyclin D1 delayed the onset of MCL cells engraftment, impaired tumour growth and altered tumour cells homing towards the lymphoid compartments." (PMID 29066743, 2017). "We observed a positive correlation between a lack of cyclin D1 expression and tumor grade and proliferation, which confers an aggressive course of disease." (PMID 29140993, 2017). "Moreover, mRNA levels of the Wnt target genes CCND1, AXIN2 and c-Myc were dramatically decreased in the tumor with low TGIF1 levels." (PMID 29050273, 2017). "Sixteen cases were non-evaluable due to lack of tumor material, leaving 364 samples for Cyclin D1 analyses." (PMID 28528450, 2017). "Patients with tumor that overexpressed cyclin D1 showed poor overall survival as compared to patients with tumor that were negative for cyclin D1 expression." (PMID 28107179, 2017).
tumor (continued). "Furthermore, phosphorylated JAK and STAT3 in tumor tissue were both reduced after fucoidan treatment, and promoter activation of STAT3-regulated genes, such as VEGF, Bcl-xL and Cyclin D1, was also significantly reduced after treatment." (PMID 28764703, 2017). "Moreover, miR-140-5p decreased tumor growth of HCC by ablating Pin1 and its downstream target cyclin D1 in vivo." (PMID 28383568, 2017). "Furthermore, 4EBP1 and p70S6K1, which are regulated by growth factor-mediated mTOR signaling, control tumor development and progression through eIF4E-mediated cap-dependent translation of tumor promoting genes, such as survivin, HIF-1α, cyclin D1, and c-Myc." (PMID 28961193, 2017). "Simultaneously, the expression of the oncogene cyclin D1 and EMT markers increased along with AEG-1, suggesting that this process may promote tumor progression." (PMID 26909607, 2016). "Furthermore, IHC staining of tumor sections of xenografts demonstrated that p27 and c-PARP were decreased, while CCND1 was increased in 5-8F/BRD7 tumors when miR-141 expression was restored compared with the miR-NC-transfected 5-8F/BRD7 tumors." (PMID 27010857, 2016). "In our study, we observed that berberine, a natural product with wide spectrum of anti-tumor activity, could promote the recruitment of SCF protein complex and Cyclin D1 in HepG2 cells and facilitate Cyclin D1 proteolysis." (PMID 27854312, 2016). "We found that cyclin D1 expression is up regulated in tumors from AKXD27 mice with retroviral insertions at Evi3 as compared to a control tumor without an Evi3 retroviral insertion." (PMID 27107743, 2016). "Regarding non-tumor cells (NIH3T3), Amblyomin-X produced minor effects in the cyclin D1 levels." (PMID 27566592, 2016). "Tumor growth inhibition was demonstrated in the IHC analysis of a subcutaneous HCC tumor, and CBT-143-S-F6F7 reduced the expression of the cell proliferation markers Ki67 and cyclin D1." (PMID 27502492, 2016). "The downregulation in the expression of tumorigenic proteins such as cyclin D1, COX-2, and survivin in tumor tissue may be due to the suppression of NF-κB activity." (PMID 26909608, 2016). "In addition, ZO-1-interacting transcription factor ZONAB, which regulates expression of several cell cycle regulatory proteins, including Cyclin D1, was enriched in cell-cell junctions between MYO1E KO tumor cells." (PMID 27329840, 2016). "Conversely, cytoplasmic expression of Ccnd1 has not been taken into account as an indicator of tumor status other than the non-proliferative state." (PMID 27105504, 2016). "Both tumor types exhibited classic histology, and similar expression patterns for expected Shh-MB neural markers (Atoh1, TUBB3 and GFAP) and Hh target genes (Gli1, Mycn and Ccnd1)." (PMID 27823583, 2016). "In contrast, sar@LIP induced the up-regulation of a broad spectrum of genes related to the positive induction of cell proliferation (CCND1, E2F3, PDGFRB and TEGT, a described BAX inhibitor), which corresponds to the tumor growth enhancement observed in vivo after sar@LIP administration." (PMID 27646588, 2016). "Finally, we found that overexpression of ANG2 resulted in changes in the expression of tumor formation-related proteins including vimentin, E-cadherin, Bim, PUMA, Bcl-2, Bax, Cyclin D1, PCNA and CD31." (PMID 27492854, 2016). "One of the potential mechanisms that underline the DNMT3B-mediated arrest involves the ability of DNMT3B siRNA to reduce the expression of different cyclins (Cyclin B1, Cyclin D1 and Cyclin E2) and to block the pRB/E2F1 pathway by inducing de-phosphorylation of RB tumour suppressor." (PMID 27764816, 2016).
tumor (continued). "Our morphological examination revealed that untreated tumor tissues showed aggressive growth and abundant Cyclin D1 expression, while TUNEL+ apoptosis foci were commonly observed in resveratrol-treated tumor tissues, which also showed a remarkable reduction of Cyclin D1 expression." (PMID 27716625, 2016). "Upregulation of cyclin D1, VEGF, MMP-9, miRNAs, and p21Cip1 showed a clear correlation with tumor cell cycle progression, vasculogenesis, metastasis, and invasion, and may contribute to malignant transformation of PAs to PCs." (PMID 27893664, 2016). "Previous studies have suggested that ZKSCAN3 directly or indirectly regulates the expression of various genes, such as CCND1, CCND2, EGFR, IGF-2, integrin-β4, NF-κB, and VEGF, all of which are known to involve tumorigenesis, tumor progression, and/or metastasis." (PMID 27447553, 2016). "The present study demonstrates that physical interactions between ARID2 and the transcriptional factor E2F1 play pivotal roles in ARID2-mediated suppression of cyclin D1 and cyclin E1, supporting the notion that ARID2 acts as a tumor suppressor by targeting the Rb-E2F signaling pathway." (PMID 27351279, 2016). "In the solid areas of MYO1E WT tumors, Cyclin D1-positive cells were distributed throughout the tissue, while in the tumors lacking MYO1E, Cyclin D1-positive cells were confined to the ducts and the periphery of tumor acini." (PMID 27329840, 2016). "The expression of the oncogene cyclin D1 and EMT markers increased with AEG-1, suggesting that this biological process may promote tumor progression." (PMID 26909607, 2016). "For other proteins such as Ki-67 and cyclin D1, tumor cells with nuclear staining, regardless of cytoplasmic staining, were regarded as showing constitutive activation." (PMID 27268017, 2016). "Herein, we report that further to the previously published findings on PG545′s ability to interfere with angiogenic growth factors, this compound also inhibits Wnt signaling within tumor cells which leads to reduced levels of β-catenin, VEGF, MMP-7 and Cyclin D1." (PMID 25669977, 2015). "Then the next question to consider is that how HCC tumor cells remain their uncontrolled proliferation without cyclin D1 overexpression in HCC." (PMID 25851350, 2015). "Finally, downregulation of cyclin D1, c-MYC, survivin, c-Met, EGFR, Src, FAK, and α-tubulin expression was observed in 786-O tumor xenografts treated with ART." (PMID 26426994, 2015). "These two studies indicated that UBE2D3 expression is involved in cell cycle regulation via the degradation of cyclin D1; in consideration of this biological behavior, the present study proposes that UBE2D2 expression levels may promote tumor development." (PMID 25789002, 2015). "Our results showed that EZH2 silencing down-regulated β-catenin, c-myc and cyclin D1, suggesting that the miR-506-EZH2 axis may suppress tumor proliferation and metastasis by inhibiting the Wnt/β-catenin pathway." (PMID 26452129, 2015). "Our results demonstrate that miR-211 is a tumor suppressor that controls expression of Cyclin D1 and CDK6, and that its downregulation results in overexpression of Cyclin D1 and CDK6 which increases proliferation ability of EOC cells to proliferate compared to normal cells." (PMID 25889927, 2015). "Of note, increased Cyclin D1, Ki-67 and SIRT1 protein levels were found in tumor homogenates obtained from G-1 stimulated mice with respect to mice treated with vehicle, however, these stimulatory effects were prevented in the group of animals receiving G-1 in combination with Sirtinol." (PMID 26225773, 2015). "Overexpression of miR-634 resulted in a decreased CCND1 protein level in A2780, A2780 DDP and primary tumor cells (derived from patient 3) and this may explain the slight increase in G1 cells at 48 h after transfection." (PMID 26576679, 2015).
tumor (continued). "Taken these observations together, CD44-singaling networks-KLF4-p21-Cyclin D1 could explain, at least in part, the molecular events behind the involvement of CD44 in maintenance of tumor initiating cells." (PMID 25605020, 2015). "The possible factors that may contribute in potential tumor invasion and metastasis are MMP-9, Bcl-2 and Cyclin D1 genes which are known to be regulated by AP-1." (PMID 26581505, 2015). "Results from immunohistochemical analysis of tumor sections demonstrated a decreased intensity-staining pattern of cell proliferation markers such as PCNA, Ki67 and cyclin D1 in fisetin and sorafenib treated tumors as compared to their respective untreated control groups." (PMID 26299806, 2015). "Higher ESR1 gene amplification is found in BC with CCND1 gene amplification in comparison with tumours without CCND1 gene amplification." (PMID 26391647, 2015). "The inhibition of tumor enlargement due to the antiproliferative action of MLT is mediated by cell cycle delay at the G0/G1 phase and a shorter duration in the S phase by reducing the levels of cyclin D1." (PMID 26295055, 2015). "The genes CCND1, CDC6 and Bmi-1, when overexpressed, promote the proliferation of tumor cells." (PMID 26317630, 2015). "In this trial, bardoxolone methyl increased the expression of NQO1 in peripheral blood mononuclear cells and decreased NF-κB and cyclin D1 levels in tumor biopsies." (PMID 26301506, 2015). "This interpretation may have prognostic value since adjacent non-tumor mammary tissue from DMBA-treated animals had also increased expression of the proliferation markers Cdk4 and Ccnd1 (cyclin D1)." (PMID 26715507, 2015). "We reported in previous study that cyclin D1 and MMP-9 expression were decreased, and caspase 3 expression was increased by overexpression of SASH1 in U251 cells, supporting the role of SASH1 as a candidate tumor suppressor." (PMID 26424902, 2015). "Tumor cells with high cyclin D1 levels have higher proliferation rate and lower nutrient requirements that tumor cells that do not express cyclin D1." (PMID 25881299, 2015). "Indeed, it was observed that it is able of binding the protein GCIP (interacting protein cyclin D1 and GRAP2), which is a tumor suppressor localized in the nucleus, which inhibits the phosphorylation of RB (retinoblastoma protein)." (PMID 25889931, 2015). "Surprisingly, mice overexpressing hMet and truncated β-catenin do not require cyclin D1 expression for tumor development, since it was shown that tumor can grow faster in its absence (cyclin D1−/− mice)." (PMID 24419005, 2014). "The signaling mechanism of TACSTD2 involved in tumor pathogenesis was first explained by activating the extracellular signal regulated kinase (ERK)/mitogen-activated protein kinase pathway, and cyclin D1 was activated as an important downstream factor of the pathway." (PMID 25202389, 2014). "In univariate analyses, lymph node positivity, surgical margin positivity, non-localized tumor, age at prostatectomy, and biomarkers CCND1, HMMR, IGF1, MKI67, SIAH2, and SMAD4 in malignant epithelium were significantly associated with time to BF." (PMID 24708576, 2014). "In the present study, it was observed that increased Cyclin D1 expression was correlated with advanced clinical stage, lymph node metastasis and deeper tumor invasion depth, but not with age, gender or histological grade." (PMID 25202365, 2014). "Of note, the same study also found that the upregulation of p57 by cDNA transfection decreased tumor growth, as demonstrated by the growth curve, flow cytometric analysis and cyclin D1 downregulation, without affecting the apoptotic machinery." (PMID 24919811, 2014).
tumor (continued). "Nonetheless, amplification of CCND1 was not a prerequisite for YAP1 gene loss, as there were several tumours with low YAP1 copy number where increased CCND1 copy numbers were not present." (PMID 24559095, 2014). "Furthermore, we found 4EGI-1 strikingly decreased cell proliferation key regulators cyclin D1 and c-MYC in breast CSC tumor cells, indicating that 4EGI-1 inhibits translation essential for cell proliferation in breast CSCs." (PMID 25115391, 2014). "Among the 46 OSC samples, the prevalence of cyclin D1 expression did not significantly vary within the three tumor differentiation stages (P>0.05)." (PMID 24348821, 2014). "In male PyVT mice, treatment with tamoxifen increased cyclin D1 expression without significantly altering tumor growth." (PMID 23755153, 2014). "When compared to the corresponding non-tumor part, β-catenin and cyclin D1 expression in tumor part were higher in 25 (45%) and 31 (55%) patients, respectively." (PMID 25160749, 2014). "Furthermore, we found that 4EGI-1 selectively inhibits translation of mRNAs encoding proteins that are enhanced in CSC maintenance, proliferation and metastasis, such as NANOG, OCT4, c-MYC, cyclin D1, CXCR4, VEGF and c-MYB, in breast CSC tumor cells." (PMID 25115391, 2014). "Tumours were evaluated with regard to invasiveness, size, axillary lymph node status, Nottingham grade, tumour proliferation (Ki67), Human epidermal growth factor receptor 2 (HER2) status, and expression of cell cycle regulators such as cyclin D1 and p27." (PMID 24708573, 2014). "While Myc or Wnt oncogenes can effectively drive tumor development irrespective of cyclin D1, genetic deletion of cyclin D1 specifically prevented tumor development driven by Her2." (PMID 25223380, 2014). "Therefore, to examine the effects of the combination of sgRNA targeting cyclin D1 and cisplatin on SCC proliferation, we performed a tumor cell viability assay." (PMID 25437003, 2014). "We next evaluated tissue from tumor bearing mice (tumor mass, spleen, intestine and kidney) by immunohistochemical analysis for the expression of CD3, CD5, CD19, CD20, CD23, CD45, CD79a, Ki-67, cyclin D1, and Pax5." (PMID 24722054, 2014). "Western blot analysis of tumor tissue from each mouse subject did not reveal a significant difference in cyclin D1 expression between treatments." (PMID 24152862, 2013). "Twelve tumours were cyclin D1-positive (12/41, 29%) and twenty-nine tumours were cyclin D1-negative (29/41, 71%)." (PMID 23672832, 2013). "Of note, the expression of Cyclin D1, one of the first identified β-catenin targets, was not altered in tumor tissue." (PMID 24171719, 2013). "Final tumor mass, Bcl-2, Bax, and Cyclin D1 protein levels in tumors were not significantly affected by Se-casein." (PMID 24152862, 2013). "As expected, DAPT treatment alone significantly decreased NICD expression (compared with the control group); however, DAPT alone only slight affected Cyclin D1, Bcl2, and Bax gene expression, while SIL had very potent effects on tumor suppression and on the expression of these proteins." (PMID 24386256, 2013).